TMEM54 (transmembrane protein 54)
Synonyms: BCLP; CAC1; CAC-1
Tractability: Antibody: UniProt predicts a signal peptide or a membrane-spanning region.
Gene: Protein-coding gene on chromosome 1 (32,894,593 to 32,901,440, reverse strand). Ensembl gene ENSG00000121900.
Subcellular location: Membrane
Subcellular location (Human Protein Atlas): Vesicles
Gene Ontology:
Molecular function: protein binding
Cellular component: membrane
Genetic constraint (gnomAD): Loss-of-function variants: 24 observed, 21.46 expected, observed/expected ratio (o/e) 1.12, 90% interval 0.81 to 1.57. The upper end of that interval is the gene's LOEUF score, 1.57, which puts it in group 6 of 6, group 1 being the genes least tolerant of losing a copy. Missense variants: 246 observed, 278.99 expected, observed/expected ratio (o/e) 0.88, 90% interval 0.79 to 0.98. Synonymous variants: 109 observed, 114.71 expected, observed/expected ratio (o/e) 0.95, 90% interval 0.81 to 1.11.
Homologues: Orthologues: chimpanzee TMEM54 (99% identical), macaque TMEM54 (98% identical), rabbit TMEM54 (88% identical), dog TMEM54 (83% identical), pig TMEM54 (82% identical), mouse Tmem54 (75% identical), rat Tmem54 (75% identical), guinea pig TMEM54 (68% identical), tropical clawed frog tmem54 (44% identical), zebrafish tmem54a (30% identical), zebrafish tmem54b (30% identical). Paralogues in human: KRTCAP3 (33% identical).
Diseases named in the same sentence as TMEM54 in open-access papers:
TMEM54 is named in the same sentence as 3 diseases in open-access papers, as found by Europe PMC text mining. Sharing a sentence is not in itself a finding about the gene and the disease. The quoted sentences say what the papers report.
nasopharyngeal carcinoma (1 paper, 2022). A carcinoma arising from the nasopharyngeal epithelium. "Interestingly, in this work, Cd is found to upregulate TMEM54, which is described with regulatory functions on miRNAs expression by in silico studies and involved in the development of nasopharyngeal carcinoma." (PMID 35163690, 2022).
cancer (1 paper, 2019). A tumor composed of atypical neoplastic, often pleomorphic cells that invade other tissues. "Surprisingly, only two genes appeared in both the “epithelial targets” and “cancer targets” tables—Tmem54 and Claudin-4, a previously experimentally validated Grhl-target." (PMID 31683705, 2019).
TMEM54 also shares sentences with these, for which no sentence is quoted: gastric cancer (1 paper).